IL17A (interleukin 17A)
Diseases named in the same sentence as IL17A in open-access papers (continued):
Sharing a sentence is not in itself a finding about the gene and the disease.
Hepatic steatosis (continued). "Results: the HFHS diet induced, in the dams, hepatic steatosis, oxidative stress (reduced catalase, elevated protein oxidation) and the activation of pro-inflammatory pathways (p38-MAPK), along with imbalanced circulating cytokine concentrations (increased IL-6 and decreased IL-5 and IL-17A)." (PMID 38671859, 2024).
multiple myeloma (49 papers, 2010 to 2025). "In line, high serum concentrations of IL-17A in myeloma patients are associated with severe bone osteolytic disease and higher fracture incidence than those with lower IL-17A concentrations." (PMID 38690280, 2024). "A clinical trial utilizing the anti-IL-17A antibody alone or with the anti-PD1 antibody in multiple myeloma patients is ongoing." (PMID 38349411, 2024). "In concordance, they also demonstrated that inhibition of SRC-3 activity suppresses IL-17A expression in γδ T cells, reduces the multiple myeloma progression in mouse models and enhances the efficacy of bortezomib." (PMID 37958417, 2023). "We demonstrated that IL-17A, a highly microbiota-dependent cytokine, is pathogenic after ASCT and acts directly on myeloma cells in the BM to promote relapse." (PMID 33777050, 2021). "IL-17A, known to promote multiple myeloma cell proliferation, was highly secreted by primary myeloblasts co-cultured with MΦs." (PMID 34771453, 2021). "In mice, IL-17A inhibition with monoclonal antibodies (mAbs), both in untreated myeloma and after ASCT, attenuates myeloma progression, thus representing a potential therapeutic strategy that is under clinical investigation (NCT03111992)." (PMID 33777050, 2021). "Secukinumab, an IL‐17A‐neutralizing antibody, is approved for a variety of inflammatory diseases and has shown efficacy for multiple myeloma treatment in a preclinical study." (PMID 29689643, 2018). "A clinical trial is now exploring the efficacy of the anti-IL-17A antibody in multiple myeloma." (PMID 39906741, 2024). "Also, interleukin-17 (IL-17) and Th17 has been shown tumor-promoting effect interleukin-17A producing T helper 17 cells are significantly elevated in blood and BM in multiple myeloma and IL-17A promotes MM cell growth via the expression of IL-17 receptor." (PMID 37928417, 2023). "In addition to the critical role of IL-17A in regulating metastasis of NSCLC, some evidence has supported the proliferative role of IL-17A in cancer such as multiple myelomas." (PMID 37444399, 2023). "However, more clinical studies need to be performed to further prove the influence of serum IL-17A levels on multiple myeloma patients." (PMID 36119497, 2022). "In non-solid tumors, IL-17A was also reported to increase multiple myeloma cell viability via upregulating spleen tyrosine kinase." (PMID 37444399, 2023). "Such protective anti-myeloma immunity was clone-specific and mainly conferred by IFNγ-secreting CD8+ T cells, also being further enhanced by a CD137 agonist and IL-17A inhibition, thus representing a potential therapeutic approach to improve the autologous graft-versus-myeloma effect." (PMID 35563634, 2022).
primary immunodeficiency (48 papers, 2014 to 2025). "Interestingly, patients with IL-17 primary immunodeficiencies, specifically IL-17A and IL-17F, develop characteristic C. albicans mucocutaneous infections, demonstrating a crucial role for this cytokine family in mediating antifungal immunity." (PMID 37998910, 2023). "The five pathways that had the strongest positive correlation with IL17A expression: primary immunodeficiency, antigen processing and presentation, cytokine-cytokine receptor interaction, intestinal immune network for IgA production, and hematopoietic cell lineage." (PMID 35902909, 2022).
Chronic colitis (47 papers, 2009 to 2026). A chronic inflammatory disease of the large intestine (colon, cecum and rectum). "In contrast, the neutralization of IL-17A alleviated chronic colitis in mice with STAT3-deficient Treg cells and decreased innate immune colitis after H. hepaticus infection." (PMID 36532769, 2022). "Although weight loss was similar at the 9th week between the two chronic colitis mouse models (T cell transfer from WT mice vs. T cell transfer from Il17a−/− mice), the proportions of ILCs in the intestinal lamina propria were different." (PMID 31941937, 2020). "Although we showed that blocking IL-17A function may be associated with upregulation of Il6 and recruits RORγt+ ILCs in chronic colitis models, the pathogenic relevance of these findings should be investigated further." (PMID 31941937, 2020). "Both cytokines have a redundant but unequal pathogenic role in gut inflammation and balanced inhibition of IL-17A and IL-17F represents promising goal for therapy development in chronic colitis." (PMID 39354587, 2024). "In accordance with acute colitis, proinflammatory factor levels (e.g., IFN-γ, TNF-α, IL-17A, IL-1β and IL-6) were obviously elevated in chronic colitis mice compared to those of normal mice." (PMID 38396052, 2024). "Our previous investigation revealed that the therapeutic effects of SSW were mediated by depressing the levels of IFN-γ and IL-17A in acute UC mice models and upregulating the content of IL-22 in chronic colitis." (PMID 34956391, 2021). "In contrast to mice with acute colitis, the expression of IFN-γ mRNA in the splenocytes of DSS-treated mice with chronic colitis decreased, whereas the expression of IL-17A expression in the splenocytes increased slightly." (PMID 34488863, 2021). "Our previous study indicated that the KO mice developed spontaneous chronic colitis, which was characterized by the acquisition of IL-17A and TNF-α production in these animals." (PMID 32208434, 2020). "In the validation study using anti-IL-17A antibody, chronic colitis was induced in all the Rag2−/− mice that received T cells." (PMID 31941937, 2020). "In the absence of T-bet, particular microbes trigger overproduction of colonic TNF-α, which drives chronic colitis that is mediated by innate lymphoid cells preferentially producing IL-17A." (PMID 23063332, 2012). "A similar downregulation of Il17a was also seen in chronic colitis." (PMID 39113810, 2024). "In the present study, significant increases in the production of IL-6, IL-12p70, IL-1β, TNF-α, IFN-γ, IL-21, and IL-17A and decreases in the production of IL-10 were observed in the chronic colitis group compared with the control group, and these changes were restored by NAM treatment." (PMID 33748287, 2021). "Therefore, we aimed to evaluate the impact of blocking IL-17A function in acute and chronic colitis mouse models; to this end, we utilized Il17a−/− knockout mice." (PMID 31941937, 2020). "Therefore, additional targets besides IL-17A are required to control intestinal inflammation in chronic colitis." (PMID 31941937, 2020). "Anti-IL-17A therapy in patients with chronic colitis seems to be unable to improve inflammation, perhaps because it may induce RORγt+ ILCs." (PMID 31941937, 2020). "Chronic colitis was induced in Rag1 KO mice by passive transfer with CD45RBhiCD4+CD25– naïve T cells from C57BL/6J mice exhibiting severe body weight loss, loss of crypts in the colonic mucosa, infiltration of inflammatory cells, and higher levels of IL-17A and IFN-γ production by LPMCs." (PMID 34336843, 2021). "The concentrations of IFN-γ, IL-21, and IL-17A were significantly lower, while the concentration of IL-10 was significantly higher, in the NAM+chronic colitis group than in the chronic colitis group." (PMID 33748287, 2021).
Chronic colitis (continued). "Regardless of whether there was anti-CD3/CD28 antibody stimulation, IFN-γ, IL-17A, and IL-21 were significantly decreased (P < 0.05), and IL-10 was significantly increased in the chronic colitis + Se-enriched L. acidophilus group compared with the chronic colitis group (P < 0.05)." (PMID 34532332, 2021). "To determine the effects of blocking the function of IL-17A in chronic colitis, we induced colonic inflammation in Rag2−/− mice via a transfer of CD4+CD45RBhi T cells isolated from WT or Il17a−/− mice." (PMID 31941937, 2020). "We found that hUCMSCs decreased serum cytokine IL-17A and chemokines Gro α, MIP-1α, MIP-2, and eotaxin in comparison to PBS in acute colitis (day 8) and chronic colitis (day 25)." (PMID 30967579, 2019). "SJMHE1 treatment decreased the expression of IL-17A mRNA and increased the expression of IL-10 mRNA in the splenocytes and colon compared with the respective expression levels in the DSS- and/or DSS/PBS-treated mice with chronic colitis." (PMID 34488863, 2021). "In contrast, the severity of chronic colitis was not affected by T cell transfer from Il17a−/− mice or anti-IL-17A therapy." (PMID 31941937, 2020). "In our study, we found that the proportions of ILCs other than RORγt+ ILCs (e.g., ILC1s) were also increased in mice with chronic colitis in the absence of IL-17A." (PMID 31941937, 2020). "In cases of chronic colitis, however, disruption of epithelial barrier integrity and activation of ILC may worsen disease activity due to treatment with anti-IL-17A therapy." (PMID 31941937, 2020). "Blocking IL-17A function did not attenuate chronic colitis, although it did reduce intestinal inflammation in acute colitis and in the early phase of chronic colitis." (PMID 31941937, 2020). "The level of IL-17A with anti-CD3 and anti-CD28 mAb stimulation was noticeably reduced in the IL-33-treated chronic colitis group compared with the control group, while a similar concentration of IL-17A without any stimulation was observed in these two groups." (PMID 30539029, 2018). "Furthermore, we detected IFN-γ or IL-17A-producing CD4+ T cells in the MLN of IL-33-treated and untreated chronic colitis mice." (PMID 30539029, 2018). "We also assessed whether RORγt+ ILCs are recruited in the absence of IL-17A in our chronic colitis mouse model." (PMID 31941937, 2020). "To determine whether the increase in the proportion of Lin-RORγt+ lymphocytes is a characteristic finding in the chronic colitis model, we analyzed colonic lamina propria cells from WT and Il17a−/− mice with and without DSS treatment." (PMID 31941937, 2020). "Besides, IL-17A blockage may increase the proportion of RORγt+ ILCs (which include CD4+LTi cells) and ILC1s, thereby eventually worsening chronic colitis." (PMID 31941937, 2020). "In the intestinal lamina propria, CD4+LTi cells may play a major role in the development of chronic colitis in the absence of IL-17A." (PMID 31941937, 2020). "Our study also demonstrated that blocking IL-17A function did not attenuate chronic colitis." (PMID 31941937, 2020). "In conclusion, RORγt+ ILCs may have an important role in the pathogenesis of chronic colitis in the absence of IL-17A." (PMID 31941937, 2020). "RORγt+ ILCs may have an important role in the pathogenesis of chronic colitis in the absence of IL-17A." (PMID 31941937, 2020). "RORγt+ ILCs and transformed ILC1s may eventually worsen intestinal inflammation via IL-22 and IFN-γ, respectively, in chronic colitis when IL-17A is absent." (PMID 31941937, 2020). "Although statistical significance was not achieved in the comparison between the T cell transfer with anti-IL-17A antibody group and the group that did not receive anti-IL-17A antibody due to a small sample size, administration of anti-IL-17A antibody could not attenuate chronic colitis." (PMID 31941937, 2020).
Cirrhosis (47 papers, 2010 to 2026). A chronic disorder of the liver in which liver tissue becomes scarred and is partially replaced by regenerative nodules and fibrotic tissue resulting in loss of liver function. "Cytokines such TNF-α, IL-10 and IL-17A are well described in association with chronic hepatitis, cirrhosis and HCC in combination with other proinflammation cytokines." (PMID 33435966, 2021). "Cytokine levels of IFN-α2, IFN-γ, TNF-α, IL-6, IL-8, IL-10, IL-17A, IL-18, IL-23, and IL-33 were significantly elevated in patients with decompensated cirrhosis compared to patients with compensated cirrhosis." (PMID 38077228, 2023). "Using human liver tissue microarrays with cirrhosis, we further examined the expression levels of IL-17A, IL-17R, RORγt, STAT3 and p-STAT3 in 5 samples of normal liver tissue and in 22 samples of cirrhosis tissue by immune-histochemical staining." (PMID 28039485, 2017). "Recent studies demonstrated that IL-17a was overexpressed in patients with cirrhosis induced by HBV and/or HCV." (PMID 28465467, 2017). "Nevertheless, the plasma concentration of IL-17A was 1.5-fold higher in the AH patients than in the healthy controls (p<0.01); but a similar concentration was detected in the cirrhosis patients." (PMID 23372820, 2013). "We found higher frequencies of IL-22-producing T helper cells in AH patients (median 1.7%) than in cirrhosis patients (1.0%, p = 0.03) and healthy controls (1.0%, p = 0.01), and a 1.5-fold increase in the plasma concentration of IL-17A in AH compared with healthy controls (p<0.01)." (PMID 23372820, 2013). "In this prospective observational study, we analyzed circulating levels of IL-23, IL-17A, IL-17E, IL-17F, IL-1β, and IL-1RA in 127 patients with compensated cirrhosis, acute decompensation (AD), or ACLF in the absence of active infection." (PMID 41200179, 2025). "Thus, it is possible that patients with LSM ≥25kPa had a lower production of IL-2, TNF-α, and IL-17A due to the taxing effect of bacterial translocation on the immune system, which may induce immune dysfunction and a lower production of key cytokines during severe cirrhosis." (PMID 30400258, 2018). "Additionally, patients with cirrhosis who had LSM ≥25 kPa showed the lowest values of plasma cytokines [Th1 (IL-2 and TNF-α) and Th17 (IL-17A)]." (PMID 30400258, 2018). "Additionally, HIV/HCV-coinfected patients with advanced cirrhosis (LSM ≥ 25 kPa) had the lowest plasma values of cytokines related to Th1 (IL-2 and TNF-α) and Th17 (IL-17A) response." (PMID 30400258, 2018). "Moreover, a positive correlation was observed between IL-17A and p-STAT3 levels in these cirrhosis tissues." (PMID 28039485, 2017).
autism (45 papers, 2011 to 2026). Persistent deficits in social interaction and communication and interaction as well as a markedly restricted repertoire of activity and interest as well as repetitive patterns of behavior. "Previous research has demonstrated a potential association between IL-17A signaling and the manifestation of autism-like symptoms in the progeny of maternal mice subjected to immunological activation." (PMID 38002479, 2023). "Furthermore, IL17A levels are also raised in certain MAR autism-associated autoimmune diseases including rheumatoid arthritis and psoriasis." (PMID 32784803, 2020). "This may indicate that the extent of the increase in serum IL-17A levels is closely linked to the degree of the severity of autism." (PMID 22748016, 2012). "A recent study reported deficiency of Tregs in 73.3% of children with autism, an dthus, Deficiency of Tregs may be one of the reasons behind the activation of Th17 cells and the elevation of serum IL-17 A levels in children with autism." (PMID 22748016, 2012). "Previous studies indicated that prenatal MIA could increase the levels of interleukin-17A (IL-17A), which initiated immune-primed phenotypes in offspring that exhibited autism-like phenotypes and increased susceptibility to develop intestinal inflammation later in life." (PMID 36361859, 2022). "However, further research, with a larger subject population, is warranted to determine whether this increase in serum IL-17A levels plasma has a pathogenic role in autism." (PMID 22748016, 2012). "In the present study, we explored the effects of taVNS on IL-17a expression and neuroinflammation in a mouse model of autism induced by MIA, as well as its effect on the social behavior of ASD model mice." (PMID 38993386, 2024). "A study in 2012 found serum IL-17 A significant elevation in about half of their included patients with autism, which correlated with the severity of the disease." (PMID 38183030, 2024). "A study revealed that the serum level of IL-17a was significantly increased in children with autism, and genome-wide copy number variation (CNV) analysis confirmed that IL17A is one of the many genes enriched in autism patients." (PMID 38993386, 2024). "Subjects with ASD and mice exhibiting autism-like symptoms have been observed to have increased levels of IL-17A." (PMID 38002479, 2023). "Ahmed Nadeem and colleagues revealed that dysregulation in IL-6 receptors is associated with upregulated IL-17A-related signaling in children with autism, and the IL-6/IL-17A-related parameters are positively correlated with disease severity." (PMID 37139330, 2023). "In murine models, it has been shown that IL-17A plays a significant role in the induction of autism-like symptoms in the offspring of immune-activated mothers." (PMID 37108638, 2023). "It was also reported that IL-17A/IL-17R activation plays an important role in autism through the upregulation of oxidative and inflammatory mediators." (PMID 35615451, 2022). "Upregulation of intracellular enzymatic antioxidants of CD4+ T cells in autism children was revealed by a study, displaying the potential of oxidants to reduce IL-17A levels." (PMID 35844577, 2022). "A cross-sectional study by Al-Ayadhi of 45 children, aged 6–12 years, with ASD showed that the serum levels of IL-17A were positively correlated with the severity of autism, and nearly 50% of children with autism had elevated serum IL-17A levels." (PMID 35741860, 2022). "It was found in a mouse study that RORγt-dependent T cells such as Th17 cells, which produced IL-17A, played a key role in the induction of autism-like behaviors as well as an atypical cortical phenotype in offspring by MIA." (PMID 35844577, 2022). "A number of studies reported an up-regulated IL-6/IL-17A signaling pathway, indicating overactivity of Th17 cells in autism." (PMID 35844577, 2022).